MPO (myeloperoxidase)
Diseases named in the same sentence as MPO in open-access papers (continued):
Sharing a sentence is not in itself a finding about the gene and the disease.
ischemic stroke (continued). "Therefore, MPO/HOCl could be critical therapeutic targets for ischemic stroke." (PMID 38515139, 2024). "Allicin treatment (50 mg/kg) revealed to reduce TNF-α level and MPO activity, ameliorated infarct size, alleviated brain edema and improved the neurological score in the experimental MCAO ischemic stroke rat models." (PMID 32508671, 2020). "The absence of ADAMTS13 in mice with ischemic stroke has been correlated with increased myeloperoxidase activity and expression of pro-inflammatory cytokines such as interleukin-6 and tumor necrosis factor-α." (PMID 40217918, 2025). "On the other hand, in the aged mice, ischemic stroke elicited a much larger MPO-mediated response that even during the resolution stage there continued to be MPO+ cells in the ischemic area even if they are not actively degranulating." (PMID 39325942, 2024). "During the acute stage of ischemic stroke, levels of HDL-related proteins such as alpha-1 anti-trypsin, myeloperoxidase, and paraoxonase-1 may compromise the antioxidant capabilities of HDL." (PMID 39210350, 2024). "Both pharmacological MPO inhibition by 4-aminobenzoic acid hydrazide and congenital absence of MPO can decrease the final lesion volume and provide neuroprotection in rodent models of ischemic stroke." (PMID 36439687, 2022). "Here, we used the MPO inhibitor 4-Aminobenzoic acid hydrazide (ABAH) that has been previously shown in other studies to be beneficial against different disease models in vivo, such as experimental autoimmune encephalomyelitis and ischemic stroke." (PMID 35269694, 2022). "Genetic deletion or pharmacological intervention with MPO inhibitors decreased inflammatory cell recruitment, reduced infarct volume, protected the BBB integrity, attenuated neurological deficit and improved survival rates in rodent ischemic stroke model." (PMID 32508671, 2020). "Our study found MPO to be moderately positively correlated with MDA and to exhibit a circadian rhythm inversely consistent with that of SIRT1-BMAL1, suggesting that the SIRT1-BMAL1 pathway might play a certain role in the early occurrence of ischaemic stroke." (PMID 38245621, 2024). "The GMDR analysis revealed that the combination of MPO-DNA, AIM2, and IL-1β exert a synergistic effect on the prognosis of LAA stroke, which indicated NETs/AIM2/IL-1β axis may involve in inflammatory damage after ischemic stroke." (PMID 39737165, 2024). "As such, inhibiting MPO activity or congenital absence of MPO can improve neuroprotection and neurogenesis to decrease infarct size, improve functional outcomes, and lower mortality after experimental ischemic stroke." (PMID 39325942, 2024). "However, the effect aging has on MPO in ischemic stroke has not been explored." (PMID 39325942, 2024).
chronic kidney disease (37 papers, 2015 to 2026). Impairment of the renal function secondary to chronic kidney damage persisting for three or more months. "These bystander effects can be directly mediated by enzymatic activity associated with components of the NETs, including myeloperoxidase and neutrophil elastase as noted in chronic kidney disease or toxicity of degradation products including free histones." (PMID 33816549, 2021). "Myeloperoxidase (MPO), a marker mainly for neutrophil granulocytes, catalyses the formation of reactive nitrogen species and is elevated in patients with chronic kidney disease and associated with its progression." (PMID 32604873, 2020). "Previous studies have shown that MPO -463G > A (rs2333227) might be associated with chronic kidney disease (CKD) susceptibility, but sample sizes of those studies are relatively small." (PMID 30278820, 2018). "Increased myeloperoxidase (MPO) expression and activity are associated with atherosclerotic disease in patients with chronic kidney disease (CKD)." (PMID 33234591, 2021). "ANCA positivity, particularly MPO-ANCA (or P-ANCA), has been known as a risk factor positively associated with ESKD progression in MPA patients alongside higher chronic kidney disease classes and unfavourable histopathological findings." (PMID 41303729, 2025). "In conclusion, various endogenous and exogenous pathophysiological mechanisms in patients with chronic kidney diseases lead to enhanced activity of oxidative enzymes such as xanthine oxidase (XO), myeloperoxidase (MPO), and the NADPH oxidase enzymes (NOX)." (PMID 37597078, 2023). "MPO and elastase levels have been reported to be elevated in chronic kidney diseases prior to dialysis but they are enhanced in dialysis patients compared with end-stage renal failure patients." (PMID 38034546, 2023). "MPO activity is increased in chronic kidney disease patients and further enhanced in HD according to the type of membrane and contamination of dialysis fluid." (PMID 38034546, 2023). "Plasma concentration of myeloperoxidase (MPO) increases in the elderly and/or patients with several aging-related inflammatory diseases such as cardiovascular diseases, type II diabetes or chronic kidney disease." (PMID 29772765, 2018). "Background/objective: Previous studies have shown that MPO -463G > A (rs2333227) might be associated with chronic kidney disease (CKD) susceptibility, but sample sizes of those studies are relatively small." (PMID 30278820, 2018). "In this review we presented the potential role of the myeloperoxidase enzyme in the production of reactive/chlorinating intermediates and their role in oxidative damage to biomolecules in the body of patients with chronic kidney disease and end-stage renal disease." (PMID 27127544, 2016). "Elevated levels of MPO in the circulation are associated with inflammation and oxidative stress, and implicated in pathology including CVD, chronic kidney disease (CKD), myocardial ischaemia, stroke, and venous thrombosis." (PMID 39226216, 2024). "Elevated levels of MPO and its biological products are found in a variety of kidney diseases, including chronic kidney disease (CKD), pyelonephritis, and glomerulonephritis." (PMID 38275657, 2024). "A 56-year-old woman presented with myeloperoxidase-specific antineutrophil cytoplasmic antibody (MPO-ANCA) positive AAV, transfusion-dependent anemia (hemoglobin: 56 g/L), and advanced chronic kidney disease with 55% tubulointerstitial atrophy." (PMID 40901468, 2025). "In our study, we reported higher levels of markers of oxidative stress and inflammation, MPO, CU/Zn SOD and IL-6, in more severe stages of chronic kidney disease (stages G4 and G5)." (PMID 36498741, 2022). "The study included 97 MPO-AAV patients with renal involvement and 230 control patients with chronic kidney disease (CKD)." (PMID 33481903, 2021).
chronic kidney disease (continued). "However, in the recent study, within the GPA group (N = 151, 29% MPO+) patients with MPO-ANCA were older, and characterized by less prevalent ENT and neurological manifestations, increased end-stage renal disease (ESRD) and mortality." (PMID 39257888, 2024). "The positive correlation between MPO, CU/Zn SOD and IL-6 and eryptosis levels in our study population highlights the role of oxidative stress and inflammatory cytokines in the pathogenesis of RBCs’ programmed death in patients with chronic kidney disease." (PMID 36498741, 2022). "However, an analysis of the earlier studies shows that significant changes in the activity of PON-1 and MPO appear most often in the end stages of chronic kidney disease, which may explain the lack of significance in our moderately advanced group of patients with CKD." (PMID 30857306, 2019).
leukemia (37 papers, 2012 to 2026). A malignant (clonal) hematologic disorder, involving hematopoietic stem cells and characterized by the presence of primitive or atypical myeloid or lymphoid cells in the bone marrow and the blood. "MPO plays a crucial role in determining the susceptibility of leukemia cells to parthenolide-induced apoptosis." (PMID 40338916, 2025). "Increased levels of MPO are also associated with many other types of cancer, e.g., leukaemia and gynaecological cancers, including ovarian cancer." (PMID 37513924, 2023). "Histomorphological examination of the specimen from the right-sided temporectomy revealed multiple brain parenchymal hemorrhages with dense clusters of leukemia cells that stained positive for myeloperoxidase (MPO)." (PMID 41153376, 2025). "The presence of CD34, cytoplasmic CD3, and partial myeloid markers (CD117, MPO) was crucial in classifying this leukemia as T/Myeloid MPAL." (PMID 40605863, 2025). "While these studies did not address the involvement of CD11b in the pro-apoptotic action of MPO, it is plausible that ligation of CD11b exerts opposing actions in primary and leukemia cells likely by shifting the balance of pro-survival and pro-apoptosis cues." (PMID 36421487, 2022). "In contrast to generating survival cues in human neutrophils, MPO was reported to promote apoptosis in HL60 leukemia cells, and this was partially inhibited by the inactivation of MPO with 4-ABAH or methimazole." (PMID 36421487, 2022). "Of note, the bulk leukemic population had features typical of AML, with blast morphology, Mac1 and Gr1 co-expression, myeloperoxidase positivity, invasion of parenchymal organs, and the ability to transmit leukemia to WT recipients." (PMID 31748606, 2019). "It has been reported that MPO can provoke caspase-3 activation and apoptosis in HL-60 human leukemia cells." (PMID 22389696, 2012). "While this may seem straightforward, assessing adequate MPO expression for myeloid lineage commitment can be challenging due to the variability seen in MPO expression patterns across different leukemia cases." (PMID 40075717, 2025). "This leads to the possibility that myeloperoxidase inhibitors could reduce the rate of therapy‐related leukaemia by protecting haematopoietic cells from TOP2 poison‐mediated genotoxic damage while preserving the anti‐cancer efficacy of the treatment." (PMID 38531625, 2024). "Etoposide is activated by the myeloid‐specific enzyme myeloperoxidase (MPO) to more DNA damaging forms, and we show that MPO inhibition reduces etoposide‐induced DNA damage in bone marrow mononuclear cells in which leukaemias may arise." (PMID 38531625, 2024). "However, the myeloid markers (e.g., MPO) eventually showed positivity and the leukemia completely changed its lineage to AML." (PMID 35402256, 2022). "MPO can stimulate caspase-3 activation-mediated apoptosis in HL-60 human leukemia cells." (PMID 29670633, 2018). "Together these results support targeting myeloperoxidase activity to reduce genetic damage leading to therapy-related leukemia, a possibility that is enhanced by the recent development of novel specific myeloperoxidase inhibitors for use in inflammatory diseases involving neutrophil infiltration." (PMID 27974636, 2017). "The most obvious characteristic in APL leukemia cells was the positive expression of MPO (+, 100%), CD13 (+, 100%; and homogeneous mean fluorescent intensity (MFI)), CD33 (+, 100%; and homogeneous MFI), CD64 (dim, 100%; and homogeneous MFI), and negative expression of CD11b (0%) and CD10 (0%)." (PMID 29113330, 2017). "In contrast to these findings, MPO was found to mediate apoptosis in HL60 leukemia cells." (PMID 23508943, 2013). "In addition, MPO could induce the activation of caspase-3 and apoptosis in HL-60 human leukemia cells." (PMID 38919521, 2024).
leukemia (continued). "May-Grünwald-Giemsa staining of peripheral blood smears, myeloperoxidase staining of spleen imprints and flow cytometric analyses of Gr1 and Mac1 expression showed the typical morphology and myeloid markers expression patterns of PR and AE leukemia." (PMID 33327558, 2020). "Blasts in this subtype of leukemia express B-, T-, and myeloid-lineage-defining markers, such as CD3, CD19 plus 1, or a more designated B-lineage marker, and MPO or two or more monocytic markers." (PMID 40075717, 2025). "One patient with ALL relapsed in the bone marrow after remission, with relapsed leukemia cells resistant to salvage ALL treatment; some (23%) appeared weakly positive for myeloperoxidase (MPO) staining." (PMID 40123764, 2025). "LSP1 was highly expressed in most leukemia cell lines (shown in the dotted box), while IL1R2, MPO, and CRIP1 were highly expressed in one or two leukemia cell lines." (PMID 37691822, 2023). "Six stages of leukemia differentiation-arrest categories based on CD34, CD117, CD13, CD33, MPO, and HLA-DR expression were identified in two independent cohorts of 2087 and 1209 AML patients." (PMID 35973983, 2022). "Here, the biodegradability of 2D Au nanosheets (AuNS) by enzymatic catalysis of human myeloperoxidase (hMPO) using a test-tube model and an in vitro model with MPO-secreting neutrophil-like cells (present in the blood) differentiated from human leukemia (HL-60) cells has been reported." (PMID 42052403, 2026). "Leukemia cutis may also show a pcALCL-like histology but usually expresses TdT, CD34, and/or CD117, and myeloid lineage markers such as myeloperoxidase." (PMID 32013101, 2020). "These factors have led to the hypothesis that myeloperoxidase inhibition could protect hematopoietic cells from TOP2 poison-mediated genotoxic damage and, therefore, reduce the rate of therapy-related leukemia." (PMID 27974636, 2017). "In addition, the significantly decreased salivary activities of MPO and peroxidase were presented in leukaemia children with mucositis compared to those without mucositis." (PMID 37569455, 2023). "While the involvement of Mac-1 in the pro-apoptosis action of MPO has not been elucidated, Mac-1 may play opposing roles in determining the fate of primary and leukemia cells likely by shifting the balance of pro-survival and pro-apoptosis cues." (PMID 23508943, 2013). "If these criteria are not met, we designate the leukemia based on its single lineage determination while noting that a proportion of blasts express multiple myeloid lineage markers, including dim and variable MPO, which do not meet the current criteria for biphenotypic blasts." (PMID 40075717, 2025).
metabolic syndrome (37 papers, 2008 to 2025). A cluster of metabolic risk factors for CARDIOVASCULAR DISEASES and TYPE 2 DIABETES MELLITUS. "Elevated MPO activity in the liver and plasma has been associated with metabolic syndrome and cardiovascular and liver disease in MASLD." (PMID 39959811, 2024). "Recent research indicates that MPO deficiency improves most inflammatory diseases, including pulmonary inflammation, cardiovascular disease and metabolic syndrome." (PMID 37344492, 2023). "The division of patients into groups according to the increasing concentration of MPO caused the selection of patients along with deteriorating inflammatory markers and worsening dyslipidemia and dyslipoproteinemia." (PMID 29618370, 2018). "The division of patients into groups according to the increasing concentration of MPO caused the selection of patients with deteriorating inflammatory markers which accompanied deteriorating dyslipidemia and dyslipoproteinemia." (PMID 29618370, 2018). "Here, we summarize the usage of MPO-deficient mice in the components of metabolic syndrome." (PMID 39861371, 2025). "Dyslipidemia and dyslipoproteinemia lead to inflammation by increasing MPO levels, lowering apoAI and HDL, and impairing HDL function." (PMID 41473738, 2025). "The observed disparities in periodontal parameters and salivary biomarkers like aMMP‐8 and MPO reveal a potential bidirectional relationship between metabolic syndrome and oral health." (PMID 38852177, 2025). "Previous studies have investigated the modifications of MPO levels after dietary intervention and aerobic exercise in obese subjects and subjects with metabolic syndrome (MetS)." (PMID 37887393, 2023). "Increased levels of serum myeloperoxidase were previously observed in patients with metabolic syndrome, indicating that inflammation is intensified in this patient population." (PMID 34354700, 2021). "BMI and metabolic syndrome have been also associated with oxidative stress (MDA, MPO, CAT) and pro-inflammatory markers (IL-6, high sensitivity C-reactive protein)." (PMID 32824349, 2020). "The reduction of the myeloperoxidase activity mediated by the LRE points to the reduction of the oxidative stress induced by dyslipidemia, since the production of this enzyme during LDLox phagocytosis produces RE, which contributes to atherogenesis." (PMID 30781884, 2019). "The results suggest that moderate dyslipidemia and dyslipoproteinemia deepening of inflammation and inflammation slowly induce increase MPO concentration which decrease apoAI and HDL-C level and disturb HDLs function." (PMID 29618370, 2018). "The present study evaluated the cardiometabolic and redox balance profiles in patients with Metabolic Syndrome compared to apparently healthy individuals, and the participation of the myeloperoxidase/hydrogen peroxide axis in systemic lipid peroxidation." (PMID 25386227, 2014). "In summary, Metabolic Syndrome patients exhibited evident systemic redox imbalance compared to controls, with the possible participation of the myeloperoxidase/hydrogen peroxide axis as a contributor in lipid peroxidation." (PMID 25386227, 2014). "Dyslipidemia, and inflammatory markers: high-sensitivity C-reactive protein (hs-CRP), myeloperoxidase (MPO), lipoprotein associated phospholipase A2(Lp-PLA2), and lipid peroxides (LP) are insufficient to predict the onset, extent, and prognosis of CHD." (PMID 18489792, 2008). "Despite these promising data, further studies are required to understand whether and how MPO inhibition could be used as a novel potential treatment of metabolic syndrome." (PMID 39861371, 2025). "While prior evidence links metabolic syndrome and clinical periodontal parameters, we aimed to advance etiopathogenic understanding by incorporating proinflammatory oral fluid biomarkers aMMP‐8, tMMP‐8, and MPO alongside clinical parameters." (PMID 38852177, 2025).